CD4 (CD4 molecule)
Diseases named in the same sentence as CD4 in open-access papers (continued):
Sharing a sentence is not in itself a finding about the gene and the disease.
lupus (continued). "A high proportion of activated lupus cells (particularly CD4 T cells and DCs) expressed COX-2, and it appeared that apigenin caused depletion of these COX-2-positive cells." (PMID 19405952, 2009). "In this study we isolate and expand CD4+CD25+ T cells from 29-week-old lupus prone B/W mice to assess the function of this more comprehensive, but less pure Treg population." (PMID 19551149, 2009). "The phosphopeptide P140 issued from the spliceosomal U1-70K snRNP protein is recognized by lupus CD4+ T cells, transiently abolishes T cell reactivity to other spliceosomal peptides in P140-treated MRL/lpr mice, and ameliorates their clinical features." (PMID 19390596, 2009). "Of note in small uncontrolled trials of systemic lupus erythematosus patients, it has been reported that rituximab reduces activated CD4+ cells in parallel with B cells." (PMID 19715572, 2009). "In B/W mice with active lupus, the frequency of natural Tregs, as measured by Foxp3+ expression, was 96±2% in the cells identified by CD4+CD25+CD62LHI expression." (PMID 19551149, 2009). "CD4+ T cells from patients with active lupus overexpress LFA-1, perforin, CD70, and CD40L because of demethylation of the same sequences demethylated by a Dnmt inhibitor." (PMID 18560522, 2008). "Lupus patients have higher numbers of CD4+ T cells but lower numbers of CD8+ T cells, which produce interferon-α in response to EBV." (PMID 18560522, 2008). "It is contained in peptides recognized by human autoreactive T cell clones and CD4+ T cells from lupus patients." (PMID 17963484, 2007). "The tolerogenic peptide P140, which is recognized by lupus patients' CD4+ T cells and known to protect MRL/lpr mice, is able to thwart emergence of intermolecular T-cell spreading in treated animals." (PMID 17963484, 2007). "Previous work from our laboratory demonstrated that peptide 131–151 of the spliceosomal U1-70K protein as well as a peptide analogue containing a phosphoserine residue at position 140 (peptide P140) are recognized by CD4+ T cells from lupus mice." (PMID 17963484, 2007). "However, several traits displayed cell-type specificity, such as allergic sensitisation, mouth ulcers, and IgG glycosylation in ILC3s, and primary biliary cirrhosis, rheumatoid arthritis, and systemic lupus erythematosus in CD4+ T cells." (PMID 41573945, 2026). "Whether this mechanism is operative in the cGVHD lupus model, where donor bm12 CD4+ T cells activated by host MHC II provide cognate help for host B cells to initiate lupus, requires further investigation." (PMID 39995666, 2025). "It would be of interest to investigate whether MBD2 inhibitors can reverse the demethylation of cytokines and other genes in CD4+ T cells from lupus patients." (PMID 40533455, 2025). "Thus, our findings strongly indicated that BTN3A1 is functionally indispensable in promoting CD4+ T cells proliferation and apoptosis in the lupus‐like mice." (PMID 40959207, 2025). "Moreover, altered epigenetic programing in naïve CD4+ T cells from lupus patients has been reported, whereby hypomethylation of interferon-regulated genes results in increased transcriptional accessibility of IFN genes that promote disease." (PMID 39866877, 2025). "Moreover, we found that hUC‐MSCs significantly downregulated the basal glycolysis and basal proton efflux rate in the CD4+ T cells of lupus patients with moderate and severe disease activity." (PMID 40801323, 2025). "In CD4+ T cells from SLE patients or lupus-prone mice, activation of the mTOR signaling pathway drives enhanced glycolysis, which promotes the differentiation of CD4+ T cells into pathogenic Th17 cells while compromising the immunosuppressive function of Treg cells." (PMID 40655145, 2025). "In this sense, STING regulates CD4+ T cell and B cell responses in the cGVHD lupus model." (PMID 39995666, 2025).
lupus (continued). "Iron overload was able to promote CD4+ T cell subpopulations proliferation, inflammatory cytokines generation, and autoantibodies generation in lupus mice, and the lupus mice treated with a high‐iron diet showed a higher proportion of CD4+ T cell subpopulations." (PMID 40959207, 2025). "Elevated levels of BATF2 have also been observed in CD4+T cells from lupus patients." (PMID 39876010, 2025). "Although CD4 T cells play an important role in lupus, most likely by providing B cell help, efforts to target CD4 T cells may be less effective than targeting of the B cells directly responsible for generating pathogenic antibodies." (PMID 39844597, 2025). "Thus, the present study highlights that MSCT exerts an early neuroprotective effect in lupus by decreasing the number of systemic IFN-γ–producing CD4+ T (Th1) cells and reducing the entrance of IFN-γ into the brain." (PMID 40048256, 2025). "Similarly, targeting CD4+ or CD8+ T cells with 5-azacytidine improves lupus pathology through distinct pathways in MRL/lpr mice." (PMID 40303350, 2025). "Microbiota-mediated skewing of tryptophan catabolism modulates CD4+ T cells in lupus-prone mice." (PMID 38628865, 2024). "To examine these alternative hypotheses, we generated single-cell multiome chromatin accessibility and nuclear RNA data from sorted CD45RA+CD27+CD4+ T cells in 3 healthy and 6 lupus participants." (PMID 39688922, 2024). "Additionally, in SLE patients’ T cells, SIRT2 promotes Th17 cell differentiation and inhibits CD4+ T cell production of IL-2, correcting abnormal expression of IL-17A and IL-2, and benefiting CD4+ T cells in lupus prone mice and SLE patients." (PMID 39575238, 2024). "Moreover, compared with control MDSCs, lupus MDSCs significantly promoted the activation of splenic B cells and CD4+ T cells, and increased the percentage of germinal center B cells and plasmacytes in the spleen." (PMID 38429401, 2024). "To test whether such an integration can consistently identify potential differences in metabolic states of SLE and healthy T cells, we performed preliminary analyses on splenic CD4+ T cells from lupus-prone (TC) and healthy control (B6) mice." (PMID 38756769, 2024). "Our previous study showed that tofacitinib could ameliorate lupus nephritis (LN) in lupus mice by increasing the expression of TGFbRI and suppressing the activation of CD4+ T cells." (PMID 38494844, 2024). "Our flow cytometry results showed that treatment of lupus mice with curcumin markedly increased the percentage of Treg cells among CD4+ cells in PBMCs and lymphocytes but that there was a trend toward increased Treg cells in the spleen, but the difference was not significant." (PMID 39053932, 2024). "In systemic lupus erythematosus, the inhibition of miR-142-5p led to CD4+ T-cell activation." (PMID 37834110, 2023). "Examination of peripheral blood mononuclear cells (PBMC) from systemic lupus erythematosus (SLE) patients has revealed reduced expression of LILRB1 on CD4+ and CD8+ T cells, B cells and DCs, with LILRB1 on these cells demonstrating a diminished inhibitory function compared to healthy donors." (PMID 38022598, 2023). "It is also found that CD4+CD8+DPT cells may play a vital role in the production of autoantibodies in systemic lupus erythematosus." (PMID 37377966, 2023). "However, unchanged Dnmt1 expression and even increased Dnmt3a/b gene expression have also been identified in human lupus PBMCs or CD4+ T cells in different studies, despite the consistency of DNA hypomethylation in these lupus cells." (PMID 38153351, 2023). "This discrepancy might be best explained by the concomitant removal of activated CD25-expressing CD4+ Tcon, containing also SmD1p-specific CD4+ T cells, which are known to be increased in established lupus." (PMID 38022661, 2023).
lupus (continued). "The therapeutic efficacy of CD4+Lrig1+ T cells was confirmed in chronic IBD and lupus genetic-animal model through the adoptive transfer, which is comparable to that of CD4+Foxp3+ T cells in the IBD model and CD4+CD25+ T cells or methylprednisolone in the lupus-prone model." (PMID 37666819, 2023). "Moreover, systemic lupus erythematosus (SLE) is an autoimmune rheumatic disorder characterized by CD4+ T cell-mediated inflammatory responses that can result in tissue infiltration and organ damage." (PMID 38239344, 2023). "We found that the ten-eleven translocation protein (TET)–mediated active DNA demethylation pathway, rather than the DNA methyltransferase (DNMT)–mediated passive DNA demethylation pathway, is more likely to contribute to the DNA hypomethylation of lupus CD4+ T cells." (PMID 38153351, 2023). "Additionally, high CD300LB expression in CD4+ T cells mediates the inflammatory response in patients with systemic lupus erythematosus and heart failure." (PMID 37152990, 2023). "Furthermore, lupus patients have an increased rate of CD4+ Tregs apoptosis and a decrease in total Tregs count, and CD4+Tregs apoptosis which was positively associated with lupus disease activity." (PMID 37771588, 2023). "In lupus-prone mice, the hypoxic environment associated with renal tissue injury was shown to upregulate hypoxia-inducible factor-1 (HIF-1) in CD4+ and CD8+ T cells, resulting in metabolic reprogramming and subsequently in increased effector function and resistance to apoptosis." (PMID 37554724, 2023). "To verify our hypothesis, we adoptively transferred CD4+ T cells from C57BL/6 into BM12 mice to establish a lupus-like inflammation mouse model." (PMID 39872301, 2023). "Recent research showed that the downregulation of GDF7 in CD4+ T cells could lead to impaired suppressive functions of lupus Tregs." (PMID 37771588, 2023). "In summary, these data support that catalytic inhibition of METTL3 contributes to autoantibody production and the lupus-like phenotype in cGVHD mice, potentially by promoting CD4+ T cell activation and affecting the imbalanced differentiation of effector T cells." (PMID 37013484, 2023). "Moreover, IL-21, produced mainly by activated CD4+ T-cells, appeared to up-regulate miR-7 and miR-22 in both healthy and lupus B-cells, providing a positive feedback between activated T-cells and B-cells in lupus patients." (PMID 37215992, 2023). "In addition, the function of GrB-producing Breg cells in naïve and lupus mice was further explored using in vitro B cells-CD4+CD25− T cell co-culture assays with GrB blockade/KO of B cells." (PMID 37500293, 2023). "In lupus, CD4+ T cells are critical drivers of the antibody response and tissue injury." (PMID 37928434, 2023). "miR-199a-5p improved lupus symptoms but increased senescence of splenic CD4+ T cells." (PMID 37483618, 2023). "The importance of hypomethylation of CD4+ T cells in lupus pathogenesis was strikingly demonstrated by the findings that adoptive transfer of demethylated normal human or murine CD4+ T cells into nonautoimmune syngeneic recipient mice induced lupus-like disease." (PMID 38153351, 2023). "Based on the residues 131–151 at the same domain of this U1-70 k protein harboring the major epitopes as targets of autoreactive CD4 T cells in patients with lupus, the 21-mer synthetic peptide P140 was found protective in lupus-prone MRL-lpr mice and clinical trials by Muller and colleagues." (PMID 37922035, 2023). "In addition, CXCR4 in B cells and CD4+ T cells was upregulated more in patients with systemic lupus erythematosus than in controls." (PMID 37224769, 2023). "CD4+CD25+CD127low UCB-Tregs decrease the percentage of pathogenic monocytes, which have been shown to be associated with deterioration of kidney function in lupus patients." (PMID 37736101, 2023). "However, considering that most patients with lupus received glucocorticoid, CD4+Treg has been reported to be unaffected by drug therapy." (PMID 37771588, 2023).
lupus (continued). "These were confirmed in other NPs, by which BDF1 lupus-like mice treated with anti-CD2/CD4 antibody-coated NPs encapsulating IL-2 will lead to a higher number of CD4+ and CD8+ Treg cells, decreased expression of anti-dsDNA, proteinuria, and preserved glomeruli." (PMID 38164134, 2023). "Consequently, both SLE patients and mice prone to lupus exhibit elevated numbers of activated CD4+ T cells, and increased populations of Th1 and Th17 lymphocytes." (PMID 38137363, 2023). "Our study will thus provide direct evidence of how CD4+ T cells interacting with B cells to participate in the pathogenesis of pristine-induced lupus in the mice, which may imply new strategies for SLE treatment." (PMID 35095344, 2022). "First, we sought to determine the iron levels in lupus CD4+ T cells." (PMID 35499082, 2022). "Some lupus drugs may inhibit autoantibody production by modulating BCL-6 expression in CD4+ T cells." (PMID 35637283, 2022). "Assuming that inhibition of IRAK1 activity might relieve inflammation in lupus mouse models, we studied the lipopolysaccharide (LPS)-induced splenocytes, CD4+ T lymphocytes, and pathological symptoms of MRL/lpr mice." (PMID 36467552, 2022). "Surprisingly, lupus-associated dysregulation of the CD4+ T cell compartment was independent of direct IFN-I stimulation." (PMID 35055071, 2022). "Collectively, these emerging data indicate that CD4+ T cells in pristane-treated mice with activation markers can promote IgG production, which is critical in the induction of pathological autoantibodies in pristane-induced lupus mice." (PMID 35095344, 2022). "Reduced CD4+ T cells in the kidney of lupus-prone B6.lpr/Axl-KO mice and R428-treated anti-GBM nephritic mice suggest that they might partially contribute to the attenuated nephritis in those mice." (PMID 36578056, 2022). "We showed here that intracellular iron was increased in lupus CD4+ T cells." (PMID 35499082, 2022). "We, therefore, utilized a pristane-induced lupus mouse model to dissect whether activated CD4+ T cells from pristine-treatment mice promoted B cell activation and differentiation in the MHC and ICAM-1-dependent manners." (PMID 35095344, 2022). "In lupus T cells, and in naïve CD4+ T cells in particular, autophagic vacuoles are more abundant and autophagosome-associated microtubule-associated protein light chain 3 (MAP1LC3-II) isoform is over-expressed, indicating that macroautophagy is hyperactivated." (PMID 35720371, 2022). "Additionally, we found higher expression of AIM2‐TFH in SLE patients and further confirmed that CD4+ T cell‐Aim2 accelerates lupus symptoms mediated by regulation of TFH cell differentiation in disease models." (PMID 35343082, 2022). "Upon P140 treatment (in vivo in MRL/lpr mice and ex vivo in SLE patients), we effectively observed a lower expression of MHCII molecules in antigen-presenting cells (APCs) that are mostly B cells in lupus, a weaker activity of autoreactive CD4+ T cells, and a lower number of plasma cells." (PMID 35720371, 2022). "Heterogeneity and potential functions of CD4+ T cells in murine lupus." (PMID 35271505, 2022). "Although the local site of injury could not be fully presented with fidelity by studying T cells in the systemic level, we may provide new insights into the mechanism of CD4 + CD28− T cells related lupus tissue damage." (PMID 36320075, 2022). "In addition, our previous study demonstrated that miR-21 promotes iron accumulation in lupus CD4+ T cells." (PMID 35499082, 2022). "The dysfunction of CD4+T cells is critical in the pathogenesis of lupus." (PMID 36313363, 2022). "Within the CD4+ T helper cell population, both Th1 and Th17 cells and their cytokine products, IFNγ and IL-17, have been found to be elevated relative to Treg cells in lupus-prone mouse models." (PMID 35055071, 2022). "Moreover, one in vitro experiment exhibits that miR-451a promotes the differentiation of CD4+ T cells into T helper (Th) cells in systemic lupus erythematosus (SLE)." (PMID 35992658, 2022).
lupus (continued). "In this study, through integrated bioinformatics analysis of high-throughput sequencing data, we well-characterized the gene expression profiles in CD4+ T cells obtained from healthy controls (HC) and lupus patients, and identified crucial genes correlated with the severity of SLE." (PMID 36046235, 2022). "Furthermore, the deletion of miR-21 in CD4+ T cells alleviated the disease progression of pristane-induced lupus in mice." (PMID 35499082, 2022). "Moreover, overexpression of GLS2 corrected ROS levels and restored IL-2 production by lupus CD4+ T cells." (PMID 36211442, 2022). "Since reduced DNA methylation in the AIM2 promoter in CD4+ T cells has been observed in lupus patients, we wondered whether DNA methylation‐modulated AIM2 might regulate TFH cell differentiation, which can exert pathogenic effects on SLE." (PMID 35343082, 2022). "Interestingly, kynurenine enhances CD4+ T cells to produce IFN-γ in lupus-prone mice, whereas tryptamine stimulates mTORC1 signaling and glycolytic activity in CD4+ T cells." (PMID 35844594, 2022). "Furthermore, the mRNA levels of FTH and FTL, encoding the heavy chain and light chain of human ferritin, respectively, and the protein levels of ferritin were markedly increased in lupus CD4+ T cells." (PMID 35499082, 2022). "Given the effect of the cooperation of BCL-6 and EZH2 on miR-142-3p/5p expression in CD4+ T cells in lupus, we wondered whether EZH2 could be a therapeutic target for lupus treatment." (PMID 35637283, 2022). "T cells play a key role in lupus pathogenesis, especially the CD4 T helper (Th) cells." (PMID 33717154, 2021). "MSCs inhibited the differentiation of naïve CD4+ T cells into Tfh cells through cell–to–cell contact and the activation of iNOS, decreased the production of IL-21, alleviated lupus nephritis, and prolonged the survival rate of lupus-prone mice." (PMID 34659214, 2021). "We further explored a possible connection between interleukin-27 (IL-27), STAT3 signaling and IL-10 expression in CD4 T cells of mice with manifest lupus and found that IL-27 transcripts were increased in the spleens of ill NZB/W F1 mice compared to healthy animals." (PMID 33572870, 2021). "In addition, members of the miR-17–92 cluster were upregulated in CD4+ T cells from patients with systemic lupus erythematosus (SLE), and miR-17 affects TNF-α signaling in rheumatoid arthritis." (PMID 34039371, 2021). "Finally, we have previously shown that Esrrg expression is lower in the CD4+ T cells from the NZM2410 lupus-prone mice and the B6.Sle1c2 congenic mice carrying the NZM2410 Esrrg allele." (PMID 34156979, 2021). "It is important to note that lupus CD4+ T cells were primed to receive and activate IL-2 signaling as evidenced by the upregulation of CD25 and enhanced IL-2-induced STAT5 phosphorylation during Treg differentiation even though the CD4+CD25+FOXP3+ Treg population was depleted in SLE patients." (PMID 33763079, 2021). "To determine whether the increase in ORAI3 transcripts is disease-specific, we profiled naive CD4+ T cells from patients with gout, systemic lupus erythematosus (SLE), and PsA for the expression of ORAI3." (PMID 33568645, 2021). "In addition, epigenetic changes, such as histone hypomethylation at naive CD4+ T Cells level, have also been described to favor Th17 polarization and were early events before lupus flares." (PMID 34540858, 2021). "In contrast to 4-1BB eliciting potent effector T-cell function, 4-1BB signaling has also been shown to reduce T-cell-mediated autoimmune responses in a variety of mouse models, including EAE, and Lupus, through activation induced death or anergy induction in autoreactive CD4 T cells." (PMID 34282763, 2021). "Finally, we observed that the HVEM/BTLA ratio is significantly lower in Tregs from lupus patients compared to healthy controls, whereas ex vivo effector CD4+ T cells express higher BTLA levels." (PMID 34899718, 2021).